EGFR (epidermal growth factor receptor)
Diseases named in the same sentence as EGFR in open-access papers (continued):
Sharing a sentence is not in itself a finding about the gene and the disease.
lung cancer (continued). "Even therapies specifically targeting prevalent tumor mutations, such as the BRAF V600E mutation in melanoma and a variety of EGFR point mutations in lung cancer, only lead to relatively short-lived tumor responses." (PMID 30925887, 2019). "Epidermal Growth Factor Receptor (EGFR) mutation-positive lung cancer occurs in about 10–15% of Caucasian patients and 40–50% of Japanese patients." (PMID 31138260, 2019). "First-generation EGFR-TKIs provide significant clinical benefit in patients with these mutations, representing the first successful targeted therapy against lung cancer." (PMID 31227004, 2019). "Despite routine chemotherapy in aggressive lung cancer, almost all patients ultimately develop resistance to tyrosine kinase inhibitor because of EGFR mutation." (PMID 30898980, 2019). "All these five drugs are targeted therapies for lung cancer patients carrying EGFR:p.L858R mutation." (PMID 30407536, 2019). "BZW1 expression is associated with the EGFR mutant type in lung cancer, and knockdown of BZW1 expression significantly decreases the cellular migration ability in vitro." (PMID 31601833, 2019). "East Asian lung cancer patients (40%) showed much higher EGFR mutation frequency than Caucasian patients (20%)." (PMID 31722672, 2019). "Monoclonal antibodies targeted to EGFR and small-molecule TK inhibitors (erlotinib, gefitinib, afatinib, dacomitinib, and osimertinib) responseshave extended the lives of lung cancer patients harboring EGFR-TKI-sensitizing mutations." (PMID 31754402, 2019). "FAK-associated cross-talk between EGFR and integrin pathways have been shown to lead to tumor growth and metastasis in lung cancer." (PMID 30761269, 2019). "Intended therapeutics and prognosis monitoring for lung cancer screening in the early stage of the diagnosis relies on the detection of EGFR mutation." (PMID 31745155, 2019). "About a half of them were EGFR L858R mutation; 48.1% (26/54) in all the curated inherited lung cancers and 57.6% (19/33) in the inherited EGFR subgroup." (PMID 31703574, 2019). "The relationship between CT characteristics and lung cancer gene phenotypes has been a research area of particular interest, especially in relation to EGFR mutation." (PMID 31783917, 2019). "Collectively, these results suggest that loss of RIC8A synergizes with EGFR inhibition by attenuating YAP signaling in lung cancer." (PMID 31741433, 2019). "Lung cancer patients with mutations in epidermal growth factor receptor (EGFR) benefit from treatments targeting tyrosine kinase inhibitors (TKIs)." (PMID 31314158, 2019). "We searched four databases for all original articles on family history of malignancy and EGFR mutation status in lung cancer published up to July 2018." (PMID 31703574, 2019). "Non‐small cell lung cancer (NSCLC) positive for activating mutations of the epidermal growth factor receptor (EGFR) gene is initially sensitive to EGFR‐tyrosine kinase inhibitors (TKIs) but eventually develops resistance to these drugs." (PMID 31419057, 2019). "Our results confirm previous studies showing that EGFR mutations are more prevalent than KRAS in Chinese lung cancer patients, in contrast to previously reported Caucasian populations." (PMID 31369215, 2019). "Of specific relevance in this review are the somatic mutations of EGFR that are associated with the development of lung cancer." (PMID 30959819, 2019). "Our results showed that ORNi-PCR can detect lung cancer cells harboring two single-nucleotide EGFR mutations among a large number of cells harboring the wild-type EGFR sequence, even when the cancer cells constitute only 0.2% of the total cell number." (PMID 31426517, 2019). "Recently, various matrix-assisted laser desorption ionization-time of flight (MALDI-TOF)-based assays were approved as ultrasensitive mutation detection methods and evaluated for their ability to detect lung cancer-related EGFR mutations in cell-free DNA." (PMID 30934598, 2019).
lung cancer (continued). "The initiation of lung cancer is caused by a number of factors, including genetic alterations such as mutations in K-Ras, epidermal growth factor receptor (EGFR), anaplastic lymphoma kinase (ALK), phosphoinositide 3-kinase (PI3K), and BRAF." (PMID 30987652, 2019). "Consistent with the reported prevalence in Asian patients, 44.4% (4/9) of the lung cancer patients exhibited activating EGFR mutations." (PMID 31019892, 2019). "Altered receptor tyrosine kinase signalling, in particular EGFR and c-Met signalling have been implicated in increased pSrc signalling in cancer, particularly in lung cancer but also in breast cancer." (PMID 30999598, 2019). "Using DNA isolated from lung cancer tissue, EGFR mutations were detected in 57 patients, whereas the other 20 patients carried only wild-type (WT) EGFR alleles." (PMID 31185703, 2019). "The true frequency of EGFRex20ins mutations within the EGFR mutant lung cancer is inconsistent, contributing to roughly 4–12% of all EGFR mutations identified." (PMID 31208370, 2019). "Using genetically modified mouse models, researchers have found that lung cancers with both K-ras and EGFR mutations display immune responses with 3–5 fold increase in total infiltrating CD45+ cells compared with normal lung tissue." (PMID 32039025, 2019). "EGF-induced nuclear EGFR localization in DUOX1-deficient lung cancer cells was associated with altered dynamics of cysteine oxidation of EGFR, and an overall reduction of EGFR cysteines." (PMID 30890751, 2019). "We performed this analysis using a clinically validated PD-L1 IHC assay and clinically relevant cutoff values for PD-L1 positivity in a large single-institution study of surgically resected lung cancers with a high prevalence of EGFR mutation." (PMID 31561631, 2019). "Semaphorin 7A (SEMA7A), a GPI-AP, has been found to promote EGFR-tyrosine kinase inhibitor (TKI) resistance in EGFR-mutated lung cancer through activating the mTOR pathway." (PMID 31118109, 2019). "For example, therapeutic resistance in targeted therapies can be caused by alterations in drug targets, such as the epidermal growth factor receptor (EGFR) T790 M mutation, which leads to gefitinib resistance in nonsmall cell lung cancer." (PMID 31629402, 2019). "As is known to all abnormal activation of the EGFR signal is an important cause of lung cancer cell proliferation." (PMID 30876460, 2019). "In lung cancer, the concordance of EGFR mutation is 75.27% (79/93) and the concordance of KRAS mutations 73.77% (135/183)." (PMID 31650022, 2019). "In this study, we investigated the role of miR‐206 in IL6‐induced gefitinib‐resistant EGFR‐mutated lung cancer cell lines." (PMID 31507089, 2019). "Correspondingly, treatment of lung cancers bearing EGFR mutations with EGFR tyrosine kinase inhibitors Gefitinib and Erlotinib has been shown to be much more effective than chemotherapy." (PMID 30910997, 2019). "Repeat biopsies at the time of disease progression are useful to choose subsequent treatment for patients with EGFR mutation-positive lung cancer." (PMID 30828454, 2019). "Because the types of EGFR mutations dictate decisions about treatment with EGFR-TKIs, it is important to identify EGFR mutations corresponding to these amino-acid changes in lung cancer cells." (PMID 31426517, 2019). "In 2004, it was reported that a chemical inhibitor of the kinase activity of EGFR was effective in a subset of lung cancer patients with activating somatic mutations of EGFR." (PMID 30941048, 2019). "Although EGFR mutations in exon 18 comprise only a small proportion of all EGFR mutations, the very large number of patients with lung cancer in China means that many would harbor this mutation type." (PMID 31396478, 2019). "Lung cancer is one of the most serious threats to human where 85% of lethal death caused by non-small cell lung cancer (NSCLC) induced by epidermal growth factor receptor (EGFR) mutation." (PMID 31745155, 2019).
lung cancer (continued). "As the treatment landscape in patients with non‐small cell lung cancer (NSCLC) harboring mutations in the epidermal growth factor receptor (EGFRm) continues to evolve, real‐world health utility scores (HUS) become increasingly important for economic analyses." (PMID 31650705, 2019). "Lung cancers initially containing rare mutations of EGFR, e.g., T790M, or low frequency of MET amplification, are capable of rendering resistance to targeted therapy." (PMID 31409002, 2019). "This review focused on the mechanism for EGFR endocytosis associated with SNX1 trafficking in gefitinib-resistant lung cancer cells." (PMID 35582586, 2019). "For example, drugs associated with EGFR:p.L858R in lung cancer are searched with the builder ‘7-55259515-T-G’[variant] AND ‘lung cancer’[disease]." (PMID 30407536, 2019). "Numerous studies proved that the migration capacity of lung cancer is associated with high activation of EGFR signaling pathway." (PMID 31296849, 2019). "One such example is the identification of mutations in the epidermal growth factor receptor (EGFR) gene in lung cancer cells." (PMID 30868372, 2019). "Recently, AXL activation has been reported as a cause of resistance to epidermal growth factor receptor (EGFR)-targeted therapy in non–small cell lung cancers." (PMID 31171001, 2019). "Some small subsets investigated the association between germline BRCA1/2 mutation and EGFR-mutant lung cancer, but didn’t have positive findings due to the rare frequency of the BRCA1/2 germline mutations." (PMID 31703574, 2019). "The one major mechanism of acquired resistance to targeted therapy is the alterations in the target itself (on-target), such as second mutation T790M in EGFR in EGFR-mutant lung cancer or loss of ER function/expression in ER+ breast cancer." (PMID 31993373, 2019). "Treatment-naïve NSCLC with the EGFR T790M mutation is rare, and it has only been reported in around 2% of patients with EGFR-mutant lung cancer." (PMID 31426797, 2019). "Here, we conducted an exploratory study for label-free lung cancer pathology diagnosis and mapping of EGFR mutation spatial distribution using ambient mass spectrometry imaging (MSI)." (PMID 31555581, 2019). "Comparably, the proportion of germline T790 M mutation was much lower in Asians, i.e. 0/627 in Japanese NSCLCs and 1/12,833 in Chinese lung cancers, notwithstanding their substantially higher somatic EGFR mutation rate in the tumours." (PMID 31703574, 2019). "Real‐world health utility scores (HUS) in epidermal growth factor receptor mutations (EGFRm) non‐small cell lung cancer outpatients were similar between those treated by first‐ and second‐line tyrosine kinase inhibitors, which were superior to chemotherapy." (PMID 31650705, 2019). "It is also worth noting that LCAT1 was upregulated in a distinct subgroup of lung cancer patients that don’t have actionable mutations in EGFR, ALK, ROS or NRAS." (PMID 31779616, 2019). "The targeting therapy of EGFR signaling pathway in non-small cell lung cancer (NSCLC) has achieved a certain effect, but the two mutation of EGFR and other mechanisms of lung cancer resistance still greatly reduce the therapeutic effect of chemotherapy on it." (PMID 31839821, 2019). "In this study, we applied ORNi-PCR to simultaneous detection of the de novo L858R and acquired T790M mutations in the EGFR gene in lung cancer cells." (PMID 31426517, 2019). "Osimertinib was first approved by the U.S. Food and Drug Administration (FDA) as standard therapy for the treatment of EGFR T790M mutation-positive lung cancer." (PMID 31815659, 2019). "Guidelines recommend testing for EGFR mutation at diagnosis of advanced non–small-cell lung cancer to guide treatment." (PMID 30811306, 2019). "Osimertinib is the most recently approved EGFR-TKI, and its usage is increasing in clinical practice for lung cancer patients who have mutations in the EGFR gene." (PMID 30819142, 2019).
lung cancer (continued). "The irreversible covalent binding of neratinib to Cys-797 of EGFR overcomes resistance to the gatekeeper EGFR T790M mutation, a common resistance mechanism to erlotinib or gefitinib in L858R-mutated lung cancer." (PMID 31141894, 2019). "With respect to lung cancer, EGFR mutations are present in 14% of all LAC patients, and are mutually exclusive with KRAS mutations." (PMID 31438559, 2019). "Treatment with TKIs provides significant benefits for patients with EGFR mutations, particularly for those with lung cancer." (PMID 31452776, 2019). "In this prospective cohort study, the EGFR mutation status of 77 patients with stage IIIB or IV LUAD was first determined using lung cancer tissue." (PMID 31185703, 2019). "Other successful examples include the treatment of lung cancers harboring mutated epidermal growth factor receptor (EGFR) with EGFR inhibitors, and the treatment of melanomas bearing mutated BRAF with BRAF inhibitors." (PMID 30795816, 2019). "Molecular mechanisms underlying acquired resistance to EGFR-TKIs in EGFR-mutated lung cancers have been studied." (PMID 31428570, 2019). "Somatic driver mutations, including EGFR mutations, occur early in lung cancer evolution, and these early-occurring mutations tend to be histological-subtype-specific." (PMID 31703574, 2019). "Two surveys, 18 months apart, aimed to identify changes in EGFR mutation testing and treatment practices in non–small-cell lung cancer." (PMID 30811306, 2019). "Concurrent mutations in exon 20 (T790M) and L858R have been reported in around 0.9% of EGFR mutation-positive patients before exposure to EGFR-TKIs, and in around 24% of compound EGFR-mutated lung cancers." (PMID 31426797, 2019). "Lung cancer patients harboring G719X mutations were reported to have lower sensitivities to first-generation EGFR-TKIs and shorter survival times than those with L858R mutations or an exon 19 deletion." (PMID 30808329, 2019). "Previous studies have shown that young patients with lung cancer have a lower incidence of epidermal growth factor receptor (EGFR) mutations and a higher incidence of anaplastic lymphoma kinase (ALK) fusions, but not all studies have reported the same results." (PMID 31387567, 2019). "Several amino-acid mutations in EGFR have been identified in lung cancers, including Thr790Met (T790M), Leu858Arg (L858R), and partial deletion of the amino acids encoded in exon 19 (Ex19 Del)." (PMID 31426517, 2019). "Patients with EGFR mutations in lung cancer, resistant to erlotinib alone were more sensitive to the combination of EGFR and MEK inhibitors." (PMID 31739412, 2019). "For example, Chinese lung cancer patients tends to harbor a much higher frequency of EGFR mutations." (PMID 31349879, 2019). "Nonetheless, these results demonstrated that Ibr‐7 showed a notable anti‐proliferative effect against lung cancer cells despite their EGFR mutation type in vitro." (PMID 30663221, 2019). "Inversely, gefitinib and erlotinib retained anti-EGFR susceptibility in cetuximab-resistant head and neck and lung cancer cells." (PMID 31546690, 2019). "Representatively, the ddPCR assay for EGFR mutation in lung cancer was reported to be a highly sensitive and specific biomarker for clinical blood testing." (PMID 30733532, 2019). "Tyrosine kinase inhibitors (TKIs) are very efficient for the treatment of EGFR-mutated lung cancer and show improved therapeutic efficacy." (PMID 35520926, 2019). "Genotyping studies revealing genetic alterations in the various subtypes of lung cancer accounting for tumorigenesis led to the development of targeted therapies, namely directed to EGFR, ALK, and KRAS mutated variants." (PMID 31795465, 2019).
lung cancer (continued). "Using this technique, the mutation of epidermal growth factor receptor (EGFR) in patients with lung cancers was detected and matched with biopsy genotyping." (PMID 31247906, 2019). "Constitutive activation of the epidermal growth factor receptor (EGFR) signaling pathway has been implicated in the initiation and progression of lung cancer." (PMID 30609749, 2019). "EGFR signaling activation is frequently observed in lung cancer and EGFR mutations have been observed in many cancer cells, and a high EGFR level is correlated with an advanced stage of the disease and a poor prognosis." (PMID 31636509, 2019). "We also used molecular barcoding to investigate the status of uncommon EGFR mutations coexisting with common mutations in treatment-naïve primary lung cancer patients." (PMID 30808329, 2019). "In lung cancer cell lines (PC-9G and H1975), presenting a resistance to EGFR tyrosine kinase inhibitors due to the mutation T790M, SAHA restored the sensitivity to these inhibitors by promoting both apoptosis and autophagy-linked cell death." (PMID 31861179, 2019). "Gefitinib-resistant lung cancer cell line (PC9GR) was established from its parental sensitive line (PC9) with a traditional EGFR mutation after long time exposure to gefitinib." (PMID 31073278, 2019). "Regarding EGFR alterations, after 9–11 months of first-line therapy treatment, lung cancer cells acquire gene mutations in a way which often leads to a more increasing and metastatic tumour." (PMID 31739412, 2019). "AXL inhibition reduced the viability of EGFR-mutated lung cancer cells overexpressing AXL that were exposed to osimertinib." (PMID 30651547, 2019). "Several studies have strongly implicated APOBEC activation as a driver of mutagenesis in lung cancer progression, although this seems to be less prevalent in EGFR mutant LUAD in Asians." (PMID 30348992, 2019). "Endothelial growth factor receptor (EGFR) mutations are an essential driver of personalized therapy for patients with lung cancer and are detected in approximately 15% of Caucasian and 50% of Asian patients." (PMID 31088573, 2019). "Based on our study, a significant association between family history of malignancy and EGFR mutation in lung cancer has been observed in Asians, patients diagnosed as ADCs/NSCLCs or those with lung cancer-affected (first-degree) relatives." (PMID 31703574, 2019). "Lung cancer is one of the endangered gene associated disease where high sensitive genosensor is desired to detect a single point EGFR mutation." (PMID 31745155, 2019). "Epidermal growth factor receptor (EGFR) is widely expressed in normal epithelial tissue, but a mutant EGFR variant, which is a biomarker of lung cancer and breast cancer, can be targeted by CAR-T cells." (PMID 31637014, 2019). "Although EGFR-TKIs benefit lung cancer patients with sensitive mutations, most patients eventually develop drug resistance and relapse." (PMID 31801598, 2019). "Although there are five EGFR-TKIs (gefitinib, erlotinib, afatinib, dacomitinib, and osimertinib) currently available for the treatment of EGFR-mutated lung cancer, the optimal sequence for administration of these drugs remains to be determined." (PMID 30609789, 2019). "We also measured the serum antibody responses to EGFR protein (wild type) in lung cancer patients with different EGFR mutations." (PMID 31722672, 2019). "In this study, we applied ORNi-PCR to simultaneous detection of the two single-nucleotide mutations C2369T (corresponding to T790M) and T2573G (corresponding to L858R) in the same allele of the EGFR gene in lung cancer cells." (PMID 31426517, 2019). "Clinical trials investigating JAK inhibition in particular for EGFR‐mutated lung cancers are ongoing." (PMID 31407334, 2019).